MYOM3 (myomesin 3)
Description:
May link the intermediate filament cytoskeleton to the M-disk of the myofibrils in striated muscle.
Synonyms: FLJ35961
Tractability: No criterion of Open Targets' tractability assessment is met for any kind of drug.
Gene: Protein-coding gene on chromosome 1 (24,056,035 to 24,112,190, reverse strand). Ensembl gene ENSG00000142661.
Subcellular location: Cytoplasm, myofibril, sarcomere, M line
Subcellular location (Human Protein Atlas): Vesicles; Cytokinetic bridge; Golgi apparatus
Gene Ontology:
Molecular function: protein homodimerization activity; structural constituent of muscle; identical protein binding
Biological process: sarcomere organization
Cellular component: M band
Genetic constraint (gnomAD): Loss-of-function variants: 142 observed, 174.35 expected, observed/expected ratio (o/e) 0.81, 90% interval 0.71 to 0.94. The upper end of that interval is the gene's LOEUF score, 0.94, which puts it in group 3 of 6, group 1 being the genes least tolerant of losing a copy. Missense variants: 1,758 observed, 1,782.7 expected, observed/expected ratio (o/e) 0.99, 90% interval 0.95 to 1.03. Synonymous variants: 717 observed, 716.6 expected, observed/expected ratio (o/e) 1, 90% interval 0.94 to 1.06.
Homologues: Orthologues: chimpanzee MYOM3 (99% identical), macaque MYOM3 (96% identical), dog MYOM3 (88% identical), pig MYOM3 (88% identical), guinea pig MYOM3 (87% identical), rabbit MYOM3 (87% identical), rat Myom3 (84% identical), mouse Myom3 (83% identical), tropical clawed frog myom3 (53% identical), Caenorhabditis elegans C34F6.10 (12% identical), Drosophila melanogaster mtgo (11% identical). Paralogues in human: MYOM2 (41% identical), MYOM1 (39% identical), MYBPC3 (17% identical), MYBPC1 (14% identical), FNDC3A (14% identical), OBSL1 (14% identical), FNDC3B (14% identical), MYBPC2 (14% identical), IGSF22 (13% identical), MYBPH (8% identical), MYBPHL (6% identical).
Diseases named in the same sentence as MYOM3 in open-access papers:
MYOM3 is named in the same sentence as 15 diseases in open-access papers, as found by Europe PMC text mining. Sharing a sentence is not in itself a finding about the gene and the disease. The quoted sentences say what the papers report.
muscular dystrophy (5 papers, 2015 to 2024). Muscular dystrophy (MD) refers to a group of more than 30 genetic diseases characterized by progressive weakness and degeneration of the skeletal muscles that control movement. "In accordance with a previous study showing progressive development of muscular dystrophy in KO-Sgca mice the levels of the MYOM3 fragments in the control mice injected with PBS increased gradually with age." (PMID 26060189, 2015). "Taken together, our data suggest that MYOM3 fragments are biomarkers for the detection, evaluation and treatment monitoring of DMD, LGMD2D and potentially for other forms of muscular dystrophy associated with increased turnover of sarcomeric proteins." (PMID 26060189, 2015). "Presence of the two fragments of 100 and 130 kDa in the sera of DMD patients as well as LGMD2D patients and in different animal models of DMD (mdx mouse, GRMD dog) and other forms of muscular dystrophy indicates a conserved mechanism of MYOM3 proteolysis and release across species and diseases." (PMID 26060189, 2015). "Taken together, our data demonstrate that MYOM3 fragments are promising candidate biomarkers for monitoring therapeutic outcomes in DMD and other muscular dystrophy patients." (PMID 26060189, 2015). "Although GSDIII is not a muscular dystrophy, we found that Myom3 was elevated in the plasma of Agl–/– mice at baseline." (PMID 38015640, 2024).
dilated cardiomyopathy (3 papers, 2019 to 2022). Cardiomyopathy which is characterized by dilation and contractile dysfunction of the left and right ventricles. "Previous studies have shown that variations in MYOM1 and MYOM3 could cause cardiac abnormalities, such as hypertrophic cardiomyopathy and dilated cardiomyopathy." (PMID 35872890, 2022).
Duchenne muscular dystrophy (3 papers, 2015 to 2022). Duchenne muscular dystrophy (DMD) is a neuromuscular disease characterized by rapidly progressive muscle weakness and wasting due to degeneration of skeletal, smooth and cardiac muscle. "It has been previously demonstrated that two fragments of the myofibrillar structuralprotein myomesin-3 (MYOM3) are abnormally present in sera of Duchenne Muscular Dystrophy(DMD) patients as well as animal models of DMD including the mdx mousemodel." (PMID 34893881, 2022).
limb-girdle muscular dystrophies (2 papers, 2015 to 2019). "High levels of these MYOM3 fragments were also detected in sera from LGMD2D patients, as well as in animal models of DMD and several limb-girdle muscular dystrophies." (PMID 26060189, 2015).
lung carcinoma (1 paper, 2023). "MYOM3 has not been studied in CRC but it has been linked to clinical outcomes in renal and lung cancer." (PMID 37434131, 2023).
myonecrosis (1 paper, 2025). "By removing the mechanical protection conferred by the membrane complex normally organised around dystrophin, the duplication resulted in myonecrosis induced by membrane damage in the skeletal and heart muscles, as evidenced by the high blood levels of the two released biomarkers, MYOM3 and hs-cTnT." (PMID 40490752, 2025).
α-sarcoglycanopathy (1 paper, 2015). "The presence of the MYOM3 fragments was also analysed in serum samples of three patients with α-sarcoglycanopathy (LGMD2D)." (PMID 26060189, 2015).
myopathy (2 papers, 2019 to 2025). A disease of the muscle in which the muscle fibers do not function properly. "Given that the severe form of the WB myopathy frequently occurs around market age (week 7 of age), it is likely that the upregulation of MYOM3 in affected chickens at this stage, serves to augment the structural support of the remaining healthy myofibers in the face of the WB disease." (PMID 31748687, 2019).
infection (1 paper, 2024). The state of being infected such as from the introduction of a foreign agent such as serum, vaccine, antigenic substance or organism. "Only three proteins (GSN, PLEC, and STRIP1) and one transcript (MYOM3) related to the cytoskeleton organization and dynamics were regulated in the lower trachea after infection with huH1N1." (PMID 39247193, 2024).
MYOM3 also shares sentences with these, for which no sentence is quoted: limb-girdle muscular dystrophy type 2D (2 papers); arthrogryposis (1); dystrophin deficiency (1); hypertrophic cardiomyopathy (1); ischemic cardiomyopathy (1); tumor (1).